SPHK1 (sphingosine kinase 1)
Diseases named in the same sentence as SPHK1 in open-access papers (continued):
Sharing a sentence is not in itself a finding about the gene and the disease.
cancer (continued). "Numerous studies have shown that SphK1 is found to enhance the proliferation ability of cancer cells." (PMID 26673009, 2016). "In conclusion, we found that inhibiting SPHK1 using specific siRNAs or the pharmacological inhibitor FTY720 led to potent anti-cancer activity in NPC in vitro and in vivo." (PMID 27811359, 2016). "We investigated the expression of SphK1 depending on the ECM stiffness using various cancer cell lines." (PMID 26877098, 2016). "SPHK-1 is a decisive regulator of this sphingolipid rheostat and as such, a potent therapeutic target for cancer treatment." (PMID 27581969, 2016). "Sphingosine kinase 1 (SPHK1) has been shown to be involved in the progression of various types of human cancers." (PMID 27811359, 2016). "Rather, SphK1 activity regulates the canonical mTOR pathway, which is often dysregulated in cancer and has a crucial role in the control of HIF-2α translation." (PMID 26974204, 2016). "Sphk1 converts sphingosine to S1P, which promotes cell growth, proliferation and survival, and is a key promoter in cancer." (PMID 27811358, 2016). "In this study, the role of SphK1/S1P signaling with regard to HIF-2α was investigated in various cancer cell models including ccRCC cells." (PMID 26974204, 2016). "It has been proposed that in cancer cells SPHK1 is a master regulator of hypoxia, that acts upstream of HIF1A and thus mediates the adaptation to a hypoxic environment." (PMID 27284992, 2016). "Sphingosine kinase 1 (SphK1), an oncogenic kinase, has previously been found to be upregulated in various cancers." (PMID 26673009, 2016). "We further showed that knockout or pharmacological inhibition of SPHK1 in ovarian fibroblasts limited their activation by both cancer cells and TGF-β1, attenuating their ability to promote tumor cell migration and invasion." (PMID 26716409, 2016). "Taken together, these findings suggest that pristimerin can exert an anti-cancer activity by inhibiting HIF-1α through the SPHK-1 pathway." (PMID 27581969, 2016). "Recent studies suggest that SPHK1 activation contributes to cancer progression by increasing oncogenic transformation, cell proliferation, resistance to therapies, and metastasis processes." (PMID 27811359, 2016). "An accumulating amount of evidence demonstrates that SPHK1 is involved in cancer progression by contributing to oncogenic transformation, apoptosis, migration and resistance to treatment." (PMID 27811359, 2016). "In contrast to the substantial evidences that suggest a crucial role of SphK1 in cancer development, much less is known about the function of SphK2." (PMID 27800303, 2016). "Immunoreactivity for SphK1 was mainly localized in the cytoplasm of cancer cells, which is consistent with previous studies on SphK1 expression in other types of cancer." (PMID 26673009, 2016). "Intriguingly, plasma levels of S1P were lower in prostate cancer patients than in healthy controls, perhaps due to the reduced expression of SphK1 subsequent to decreased hematocrit featured in cancer patients." (PMID 27800303, 2016). "Recently, targeting the Sphk1 pathway with specific inhibitors or drugs is an appealing strategy for the development of effective cancer therapy." (PMID 26673009, 2016). "It has been suggested that SPHK1 plays a biologically significant role in chemo-/radio-resistance in different cancers." (PMID 27811359, 2016). "Here, we report the first evidence that the SphK1/S1P signaling pathway regulates the transcription factor hypoxia-inducible HIF-2α in diverse cancer cell lineages notably ccRCC, where HIF-2α has been established as a driver of a more aggressive disease." (PMID 26974204, 2016). "SphK1 is elevated in various types of cancers, functioning as an oncogene in tumorigenesis, however, little is known about the role of SphK1 in ACC progression." (PMID 26673009, 2016).
cancer (continued). "Aberrant SPHK1 and SPHK2 activity has been implicated in diverse malignant processes including neoplastic transformation, proliferation, and migration in numerous cancer types." (PMID 26716409, 2016). "Taken together, SphK1 expression and its biological product, S1P are critical for the regulation of invasiveness and adhesiveness in response to the mechanical status in cancer tissues." (PMID 26877098, 2016). "It has been demonstrated that S1P levels and SphK1 expression and/or activity are increased in distinct cancer types." (PMID 27800303, 2016). "Strategies that have been applied to limit the effects of SPHK1-S1P signaling in cancer include inhibition of SPHK1 and/or SPHK2 and targeting of specific S1P receptors." (PMID 26311741, 2015). "In cancer, S1P metabolism is often found to be dysregulated directing attention to the SphK1/S1P signaling pathway as a target for anti-cancer drug discovery." (PMID 25915662, 2015). "Microarray analysis showed SPHK1 was overexpressed in both cell types, suggesting SPHK1 is a putative molecular target with possible relevance to progressive human cancer." (PMID 26090720, 2015). "Immunoreactivity for SPHK1 was mainly localized in the cytoplasm of cancer cells, which is consistent with previous studies on SPHK1 expression in other types of human cancer." (PMID 26311741, 2015). "We observed that 63.8% (183/287) of the cancer tissue samples showed high SPHK1 expression and 36.2% (104/287) showed low expression." (PMID 26311741, 2015). "SPHK1 is upregulated in human cancers of many different organs including head and neck, stomach, lung, brain, colon, and ovary." (PMID 26311741, 2015). "A growing list of adverse diabetic complications is believed to be involved with high levels of SphK1/S1P expression including neuropathy, retinopathy, nephropathy, and cancer." (PMID 25866760, 2015). "We previously identified SphK1 as a modulator of HIF-1α as a key mediator of the adaptive response to hypoxia in multiple cancer cell models." (PMID 25915662, 2015). "Although the role of SphK1 in cancer progression has been extensively studied in the literature, the function of SphK2 on cell survival, growth and drug resistance has only recently been elucidated." (PMID 26337959, 2015). "There is, therefore, some evidence that cancers are characterised not only by SPHK1 up-regulation, but also often by a down-regulation of the enzymes that degrade (i.e., SGPL) or dephosphorylate S1P." (PMID 24970218, 2014). "This is supported by emerging evidence in other cancers showing the enhanced cytotoxicity of conventional chemotherapeutic agents upon inhibiting SPHK1." (PMID 25153718, 2014). "Increased SPHK1 expression supports cancer growth through direct stimulation of proliferation and survival pathways, and through modulation of the cancer microenvironment." (PMID 24970218, 2014). "SphK1 acts as an oncoprotein and facilitates Akt signaling activation in several human cancers, such as glioblastoma, colon cancer and erythroleukemia." (PMID 25109605, 2014). "In the context of cancer, ceramidases occupy an interesting position as enzymes whose activity is firstly necessary to supply sufficient sphingosine as a substrate for SPHK1, and secondly acts as a means to reduce cellular ceramide levels." (PMID 24970218, 2014). "Taken together, these reports indicate that SphK1 is involved in the regulation of cancer cell apoptosis." (PMID 25109605, 2014). "Up-regulation of SPHK1 has also been demonstrated in multiple models of acquired drug resistance in cancer cells." (PMID 24970218, 2014). "Clearly, SPHK1 is up-regulated transcriptionally in a wide array of cancer types and this promotes carcinogenesis and/or tumour growth." (PMID 24970218, 2014). "Environmental influences that up-regulate SPHK1 expression and are important in the context of cancer include inflammatory cytokines, such as TNFα and IL-1β, and hypoxia." (PMID 24970218, 2014).
cancer (continued). "Studies on the role of individual sphingolipid metabolic enzymes in oncogenic transformation and cancer phenotype have focused primarily on SPHK1 and GCS, with a number of studies focusing on acid ceramidase and other enzymes." (PMID 24970218, 2014). "Impaired sphingolipid homeostasis is a common theme for most of the cancers and overexpression of SPHK1 has been identified in multiple cancer cells derived from breast, colon, lung, ovary, stomach, uterus, kidney, and rectum." (PMID 23984075, 2013). "Further studies are required to investigate the exact mechanism of paraneoplastic changes in blood cell SphK1 activity and its implication in cancer progression." (PMID 22315056, 2012). "Sphingosine kinase-1 (SphK1), the enzyme that generates S1P has oncogenic properties, contributes to cancer progression, enhances tumour neovascularisation and metastatic potential and is associated with a poor prognosis." (PMID 22315056, 2012). "SPHK1 is overexpressed in a range of cancers and has been proposed as a novel target for cancer therapeutics." (PMID 22479372, 2012). "This perspective highlights recent findings demonstrating that sphingosine kinase 1 and S1P receptors are new important biomarkers for detection of early cancer and progression to aggressive cancer." (PMID 23316473, 2012). "Implementation of pre-clinical and clinical evaluation of SPHK1 as a novel molecular target for cancer therapy is warranted." (PMID 21936950, 2011). "Few studies by other investigators have specifically analyzed the effect of SPHK1 on invasiveness of cancer cells." (PMID 21936950, 2011). "SPHK1 is up-regulated in many types of cancers and has been suggested as a potentially new therapeutic target." (PMID 21936950, 2011). "SPHK1 was mainly localized in the cytoplasm of primary cancer cells, which is consistent with previous reports on SPHK1 expression in other cancer types." (PMID 20846391, 2010). "The regulation of SPHK1 by Runx2 probably potentiates additional aspects of the cancer phenotype, including angiogenesis (a function assisted by the Runx2 targets VEGFA and EDN2) and drug resistance." (PMID 20863401, 2010). "Many cancer cells accomplish this through an upregulation of the expression of one isoform of the kinase, SPHK1, the isoform that is thought to be responsible for S1P release into the extracellular compartment." (PMID 17024123, 2006). "However, the role of SPHK1 as a potential "metabolic immune checkpoint" across various cancers, as well as its implications for prognosis and immunotherapy, remains insufficiently explored." (PMID 41547931, 2026). "The obtained results highlight that drug C and T may be potential inhibitor candidates as SphK1 inhibitors for targeted cancer therapy." (PMID 41634337, 2026). "Additionally, in silico studies have been conducted against the important cancer drug target sphingosine kinase 1 (SphK1)." (PMID 41634337, 2026). "Cancer cells may counteract the effects of FTY720 through mechanisms such as upregulation of SphK1, which facilitates cell survival and proliferation." (PMID 40528704, 2025). "Therefore, SphK1, SphK2, and their product S1P have become potential therapeutic targets for the treatment of various diseases, especially cancer cells." (PMID 41234914, 2025). "Sphingosine kinases (SphK1 and SphK2) are key regulators of sphingolipid signaling, a pathway essential for maintaining cell structure and function but frequently deregulated in tumors, making them promising targets for cancer therapy." (PMID 40427516, 2025). "SphK1 inhibition sensitizes cancer cells to chemotherapeutic agents." (PMID 39940821, 2025). "Altogether, these findings indicate that SphK1 is a promising target for cancer therapy." (PMID 39940821, 2025). "In contrast to SphK1, SphK2’s role in cancer is not fully understood." (PMID 39940821, 2025).
cancer (continued). "In addition, a novel inhibitor SKI-178, by dual inhibition of SphK1 and S1P lyase, exhibits stronger proliferation-inhibitory effects in various cancer cell lines, providing a potential strategy for overcoming HCC drug resistance." (PMID 41234914, 2025). "Therefore, SPHK1-specific inhibitors have been developed and identified to be effective treatment for various cancers." (PMID 39875359, 2025). "Also, through a bioinformatic framework, we pointed out the alterations of SphK1 gene expression within different cancers with their impact on patient survival, and we demonstrated the protein–protein network of SphK1, elaborating its sparse roles." (PMID 38419070, 2024). "It inhibits cancer cell growth through suppressing SphK1 and nuclear factor-κB (NF-κB) p65." (PMID 38419070, 2024). "It had been expected that the high expression levels of SphK1 might result in high levels of S1P in the cancer tissue." (PMID 38542328, 2024). "Recently, SPHK1 has been found involved in metabolism modulation and cancer development." (PMID 39284838, 2024). "Cancer cells often have abundant SphK1 in the cytoplasm, and S1P production is enhanced." (PMID 38542328, 2024). "Recent research has revealed the role of SPHK1 in cancer progression 18-19." (PMID 39629135, 2024). "In this review, we comprehensively performed a molecular docking analysis for all publicly available SphK1 inhibitors to gain further understanding of their potential effect against SphK1 and their relation to the responsiveness and sensitivity of the cancer cells towards drugs." (PMID 38419070, 2024). "Therefore, targeting SphK1, and SphK2 by using inhibitors to produce low levels of S1P can be a novel protocol to minimize the cancer cell's resistance towards chemotherapeutic drugs." (PMID 38419070, 2024). "Also, several studies are required to validate SphK1 inhibition in the course of elimination of cancer drug resistance protocols." (PMID 38419070, 2024). "In addition to the regulation of apoptosis, the protein products of these genes are involved in signaling pathways that are associated with cancer development and progression, including NF-ĸB (BCL3, SPHK1, and PRKCZ) and c-MYC (PIM1 and BTG1)." (PMID 38731835, 2024). "In addition, this compound exhibitedhigh binding ability (−9.079 kcal/mol) against cancer drugtarget SphK1." (PMID 39619510, 2024). "It was reported that SphK1 could protect cancer cells from drug-induced apoptosisby increasing ceramide levels." (PMID 36909198, 2023). "SphK1 and two have been shown to be up-regulated in tumor processes, and their ablation or genetic inhibition has been shown to slow tumor growth and sensitize cancer cells to chemotherapeutic agents." (PMID 38067203, 2023). "Such upregulation, manifested by increases in GCS, AC, and SPHK1 expression, join to benefit cancer cell survival and GCS/P-gp and AC activities contributing to ceramide clearance, while SPHK1, famous for producing sphingosine 1-phosphate, is a mitogenic, anti-apoptotic player." (PMID 36980769, 2023). "Studies have shown that SphK1 inactivation/silencing could result in ceramide accumulation in cancer cells, which then inactivates Akt-mTOR cascade by activating phosphatases PP2A and PP1." (PMID 37604912, 2023). "However, the exact mechanisms by which SPHK1 regulates autophagy in these cancer cells has yet to be elucidated." (PMID 37190124, 2023). "In particular, the SphK1 isozyme, with its isoforms SphK1-a and SphK1-b, is over-expressed in numerous types of cancer cells, leading to an increase in S1P levels and a concomitant reduction in Cer levels, thus suppressing the pro-apoptotic signals and simultaneously creating a survival signal." (PMID 37569739, 2023). "Moreover, overexpression of SPHK1 has been reported in cancers of multiple organs, such as the lung and pancreas." (PMID 36348017, 2023).
cancer (continued). "Moreover, an SPHK1-driven NF-κB/IL-6/STAT3/S1PR1 amplification loop, was also essential for the development and progression of colitis-associated cancer." (PMID 36361531, 2022). "In addition, SPHK1 is also one of the important molecules involved in the invasion and metastasis of malignant tumors." (PMID 35126792, 2022). "A comprehensive analysis was conducted to assess the prognostic value of SPHK1 in human cancer." (PMID 35126792, 2022). "Similarly, the SPHK1/S1P/S1PR3 axis promoted the expansion of aldehyde dehydrogenase (ALDH)-positive cancer stem cells (CSCs) via ligand-independent Notch activation." (PMID 36361531, 2022). "A direct contribution of the metabolic product, sphingosine-1-phosphate (sphingosine-1-p), from this pathway to cancer stem cells (CSCs) had also been reported 25, 26, which is consistent with the overexpression of sphingosine kinase 1 (SPHK1) in some types of cancer." (PMID 34975334, 2022). "Our data suggest that SphK1a is important for generic SphK1/S1P functions, and SphK1b mediates specialized and/or unique pathways in a specific type of tissue and could be a biomarker for cancer." (PMID 36532885, 2022). "The little we do know is mainly derived from the few in vitro studies where the individual isoform is overexpressed and may have significance in altering SphK1 function, both in normal physiology and in cancer pathophysiology." (PMID 36532885, 2022). "Several earlier studies also suggested increased expression of the key enzymes in sphingolipid metabolism, such as SPHK1, in human cancers 25, and the direct contribution of the sphingolipid metabolic product, sphingosine-1-p, to the expansion of cancer stem-like cells." (PMID 34975334, 2022). "Potentially, from a cancer prognostic viewpoint, this information will aid our understanding of how SphK1 isoform expression may affect treatment outcomes, especially in patients with hormone-responsive cancers." (PMID 36532885, 2022). "Recent studies have revealed a role for SPHK1 in cancer progression." (PMID 36050478, 2022). "SphK1 inhibition will led to ceramide production to promote cancer cell apoptosis." (PMID 35115496, 2022). "Considering that SphK1 and SphK2 are both important therapeutic targets of NSCLC and SKI-349 is a potent SphK1/2 dual inhibitor, the current study explored the potential anti-cancer activity and the possible underlying mechanisms of SKI-349 in NSCLC cells." (PMID 35831279, 2022). "In addition, it was reported that SPHK1 promoted metastasis of cancer cells by inducing EMT, which was mediated by the FAK/AKT/MMPs axis." (PMID 35126792, 2022). "Firstly, elevated SPHK1 expression has been observed in multiple types of cancer, but the molecular mechanism of SPHK1 up-regulation in tumors remains unclear." (PMID 36361531, 2022). "Collectively, these data suggest that targeting of SphK1/S1P signaling represents a strategy that could potentially be exploited in therapeutic approaches to decrease hypoxia in cancer." (PMID 35158767, 2022). "Moreover, we analyzed the correlations between SPHK1 expression and cancer hallmarks collected from the Molecular Signatures Database (MSigDB), which is a well-defined oncogenic axis in multiple cancers." (PMID 36050478, 2022). "In addition, in order to further study the prognostic value of SPHK1 in solid tumors, we analyzed the relationship between SPHK1 and clinicopathological features that are also related to the prognosis of cancer patients." (PMID 35126792, 2022). "Eleven cohorts including 1839 cancer patients reported the impact of SPHK1 on DFS." (PMID 35126792, 2022). "Given the crucial roles of SPHK1 in cell proliferation, survival, migration, differentiation, and cancer development, it will be highly important to determine whether these SPHK1-related cellular events also involve the PLD-PA lipid pathway." (PMID 35007762, 2022).